TNF (tumor necrosis factor)
Diseases named in the same sentence as TNF in open-access papers (continued):
Sharing a sentence is not in itself a finding about the gene and the disease.
COVID-19 (continued). "In COVID-19 patients, 8-isoprostaglandin F2 alpha levels, considered as a marker of oxidative tissue damage, were elevated, and in a recent study, COVID-19 patients showed significantly higher values of hydrogen peroxide (H2O2) and NADPH oxidase 2 (NOX2) activity in serum, as well as TNF-α and IL-6." (PMID 37569625, 2023). "Cytokine detection: Comparing cytokine levels quantification in laboratory controls and patients in the 4/6-day collection after study admission, it was seen that non-severe COVID-19 cases showed an increase in IL1β, IL-6, IL-10 and TNF." (PMID 37515295, 2023). "The aim of this study was to investigate the relationship between the serum levels of a panel of pro-inflammatory cytokines consisting of IL-6, IL-8, IL-10, IL-12, TNF-α, IFN-γ and disease severity, need for oxygen therapy, ICU transfer and fatal outcome in patients with confirmed COVID-19." (PMID 37969879, 2023). "Individuals with severe and fatal COVID-19 displayed neutrophilia and lymphopenia, as well as increased levels of CRP, ferritin, and cytokines such as IL-6, IL-10, gamma interferon (IFN-γ) and TNF-α." (PMID 36852984, 2023). "TNF-α has been reported to be elevated in some COVID-19 patients, but this has not been consistent in all studies." (PMID 36851240, 2023). "TNF-α was significantly higher in all patients’ groups in comparison to HCs, whereas IFN-γ was found to be significantly decreased in the mild and severe COVID-19 groups, but significantly increased in the critical COVID-19 group compared to the HCs." (PMID 37283736, 2023). "Studies have documented significant elevation of inflammatory cytokines TNF-α, IL-6 in severe COVID-19 patients compared to non-severe cases." (PMID 38057707, 2023). "In addition, cluster 1 confirms the existence of the top ten potential anti-COVID-19 core targets (AKT1, TNF, HSP90AA1, IL-6, mTOR, EGFR, CASP3, HIF1A, MAPK3, and MAPK1); consequently, the results of the PPI and cluster network analyses are congruent." (PMID 36817449, 2023). "Lung samples from COVID-19 autopsies revealed that the inflamed pulmonary endothelium expressed IL-1β, IL-6, IL-15 and TNF-α, in contrast to non-infected tissue samples, recruiting inflammocytes along the alveolar epithelium." (PMID 37568402, 2023). "COVID-19 positive and COVID-19 negative patients had increased levels of IL-1ra, IL-6, IL-8, IL-13, TNF-α, IP-10, MCP-1, MIP-1α, and G-CSF." (PMID 36980378, 2023). "The RS between activation marker concentrations and the severity of COVID-19 are calculated by training data set Z2KP, where the activation markers are IL-17a, IL-2, GATA3, IFN-γ, IL-4, IL-10, PD_1, CD40L, RORγt, CTLA_4, CCR7, TNF-α and IL-6, respectively." (PMID 36845115, 2023). "Interestingly, postmortem lung tissues from patients with lethal COVID-19 as well as PBMCs from severe COVID-19 cases, show a type I IFN response transcriptional signature, along with TNF/IL-1β induction." (PMID 37791071, 2023). "IL-6 and TNF-α were higher in patients with low MBL and severe COVID-19 (p< 0.05)." (PMID 37138871, 2023). "Non-severe COVID-19 cases showed an increase in IL1β, IL-6, IL-10 and TNF and severely ill patients had higher levels of the cytokines IL-6, IL-10 and CXCL8." (PMID 37515295, 2023). "There was no statistical significance in the prescribing of TNF-α inhibitors between the period prior to COVID-19 and during COVID-19 (142 (61%) vs. 122 (60%) prescriptions, p = 0.722)." (PMID 37623450, 2023). "Targeting TNF-α, IL-6, MAPK1, and MAPK3 might be potential alternative treatments for CRS and COVID-19." (PMID 36817449, 2023). "Interestingly, the severely infected patients with COVID-19 were reported to have CD4+ T cells secreting lower levels of IFN-γ, IL-2, and TNF-α as compared to the patients with mild symptoms." (PMID 36679947, 2023).
COVID-19 (continued). "While the levels of cytokines in lung in COVID-19 patients have not been analyzed, the plasma levels of IL-6, TNF-α, and IL-10 were highly increased in severe COVID-19 patients with comparable levels to non-COVID-19 patients." (PMID 37724101, 2023). "In the pre-COVID-19 data set, IL1β, IL6, and TNF were found to have decreased in both groups." (PMID 37546047, 2023). "Additionally, the total numbers of lymphocytes, TCD4+, TCD8+, and NK cells were significantly decreased in patients with COVID-19 (p < 0.0001), and IL-12, IFN-γ, and TNF-α were significantly increased in patients with COVID-19 compared to controls." (PMID 37111285, 2023). "Interestingly, mounting evidence from clinical studies suggests that this PPAR agonist prevents the ARDS/ALI in COVID-19 patients by downregulating NF-κB and JAK/STAT signaling and then reducing TNF-α, IL1β, and IL6 levels." (PMID 36875108, 2023). "In COVID-19, it has been found that TNF-α levels are increased in severe compared to non-severe forms and correlate with disease severity, organ failure, and mortality." (PMID 36287942, 2022). "By comparing healthy donors, patients with mild or severe COVID-19, and patients with severe influenza, they observed that all PBMC cell types of COVID-19 displayed hyper-inflammatory signatures, marked by a TNF/IL-1β-mediated inflammatory response, as compared to severe influenza." (PMID 35663932, 2022). "The retrospective analysis included serum cytokines (interleukins; IL-1β, IL-6, IL-8 and tumour necrosis factor (TNFα)) measured using EllaTM (Bio-Techne, Oxford, UK) and PCT measured by Roche Cobas (Burgess Hill, UK) in patients admitted with COVID-19 between March 2020 and January 2021." (PMID 35500008, 2022). "Indeed, one significant mechanism with which TNF-α mediates lung inflammation and ARDS, appears to be the reduced CD4+ and CD8+ T-cell counts in patients with severe COVID-19." (PMID 36289890, 2022). "We found for CD4+ T cells, COVID-19 plasma exosomes obtained from patients upon admission stimulated production of IL-6, IL-8, and TNF-α compared to plasma exosomes from non-COVID donors, with expression of IFNγ not being significantly affected." (PMID 36526691, 2022). "Previous studies have shown that proinflammatory markers, including IL-6, IL-8, IL-1β, and TNFα, are significant predictors of COVID-19 disease severity, regardless of demographics or comorbidities." (PMID 36865568, 2022). "Furthermore, in severe COVID-19 patients, NK cells were functionally impaired due to elevated IFN-α and TNF signaling, suggesting that dysregulation of NK cells is involved in pathogenesis during SARS-CoV-2 infection." (PMID 35251030, 2022). "Similarly, in long COVID-19, higher frequencies of IFN-γ and TNF-α secreting SARS-CoV-2-specific T cells were observed as compared to patients with resolved COVID-19." (PMID 36499533, 2022). "The gene expression profile of activated lung macrophages in COVID-19 displays similarity with sHLH and MAS macrophages, and both sHLH/MAS and SARS-CoV-2 – induced cytokine storms include IL-2, IL-7, G-CSF, IP-10, MCP-1, MIP-1α and 1β, and TNF-α elevations." (PMID 35401519, 2022). "COVID-19 respiratory distress begins with an early inflammation so that pulmonary compliance is reduced by activation of intercellular inflammatory pathways, cytokine synthesis, or storm (excessive release of IL-2, IL-6, IL-7, IL-8, IL10, and TNF-α)." (PMID 35656183, 2022). "In this study concentrations of TNF-α, IL-1b, IL-2, IL-4, IL-5, IL-6, IL-8, IL-10, IL-12 p70, GM-CSF, and IFN-γ were determined by a magnetic bead assay in tear film collected from 232 symptomatic COVID-19 patients." (PMID 35508669, 2022). "Multi-organ failure may be attributed to excessive production of proinflammatory cytokines—the so-called “cytokine storm”, and interleukin 6 (IL-6) and tumor necrosis factor α (TNF-α) are the pivotal players in cytokine storm pathogenesis and COVID-19." (PMID 35277472, 2022).
COVID-19 (continued). "Other anti-inflammatory agents were also tested in their effectiveness by repurposed drugs for COVID-19 therapy and involved positive results under mediators such as inhibitors of C5, IL-1, JAK1, JAK2 and IL-33 and related to reducing release of TNF-α and IL-1β." (PMID 35843719, 2022). "In COVID-19 the use of adalimumab, a TNF-α-antibody did not reduce mortality or beneficially alter the course of the disease." (PMID 35548445, 2022). "COVID-19 patients show normal level of monocytes with activated phenotype, as evidenced by high FSC (forward side scatter) and potential to secrete cytokines, such as IL-6, IL-10, and TNF." (PMID 35883618, 2022). "During hyperoxic conditions, as occurring in COVID-19, CY1B1, whose production is enhanced by TNF-α, buffers ROS by forming oxidized adducts in DNA; therefore, COVID-19 is a condition where the role of CYP1B1 as a key regulator of ROS as signaling molecules is impaired, due to TNF-α." (PMID 36140358, 2022). "We also measured selected cytokines in the plasma sample from the patient and observed higher levels of TNF and sIL2 as compared to the healthy controls, a pattern that is distinct from patients with typical MIS-C, KD, severe adult COVID-19, or toxic shock syndrome." (PMID 35091979, 2022). "Another feature of the production of the regulatory molecules in severe forms compared with the mild course of COVID-19 is a high expression of type I IFN by classic monocytes, combined with the production of the key pro-inflammatory cytokines of the TNF and IL-1 families." (PMID 35632823, 2022). "Moreover, COVID-19 patients were reported to have reduced NK cell functional markers such as CD107a+ (a degranulation marker), granzyme B, IFN-γ+, IL-2+, and TNF-α+ compared to healthy controls." (PMID 35273641, 2022). "The TNF-α is a key element in the molecular mechanism involved in this vascular dysfunction; TNF-α is usually detected at high levels in the peripheral blood of patients with COVID-19 when compared to healthy donors." (PMID 36010572, 2022). "Under TNF and LPS priming conditions followed by fMLP stimulation, ROS production from day 1 to day 7 was much lower in both COVID-19 and CAP patients than in HCs and, importantly, significantly lower in COVID-19 than CAP patients." (PMID 35637483, 2022). "Although TNF-α did not significantly differ after comparing survivors vs. non-survivors, its levels were lower in severe than non-severe COVID-19 patients (p < 0.001)." (PMID 35207531, 2022). "The protein-protein interaction-level network obtained from the differentially expressed genes revealed elevated TNF-α signaling in the Activated CD4+ T cells, IL-6 signaling in the CD8+ TEM cells, which are indicative of elevated inflammatory response during active COVID-19." (PMID 36532041, 2022). "Among those who used anti-TNF, 2 (33.3%) people who had COVID-19 and 38 (53.5%) people who did not have COVID-19 interrupted treatment (p = 0.419)." (PMID 36161620, 2022). "The other two targets (TNF and VEGFA) that are directly related to the MAPK signaling pathway might be important targets for creating synergistic effects against COVID-19." (PMID 35678652, 2022). "On the other hand, serum levels of cytokines in COVID-19 ICU patients showed a significant increase in the production of GM-CSF, IFN-α, IL-2, IL-4, and IL-6 and a significant decrease in the levels of IFN-γ, IL-5, IL-12, IL-17A, and TNF-α." (PMID 36363785, 2022). "Furthermore, we also found elevated concentrations of hsCRP, increased percentage of elevated TNF-α, and an inverse correlation between reduced FMD and inflammatory biomarkers in survivors of COVID-19." (PMID 35237624, 2022). "Postmortem examination of spleens and lymph nodes from patients with COVID-19 has identified a lack of germinal centers, possibly due to cell death of lymphocytes driven by TNF and IFN-γ." (PMID 36419185, 2022).
COVID-19 (continued). "Moreover, in TNF-α activated monocytes, ITF3756 reduces the expression of additional biomarkers of severe COVID-19, such as PTX3, ICAM-1, S100A12, PD-L1 and MMP9, further supporting a potential role for this molecule in the treatment of the disease." (PMID 35592335, 2022). "Moreover, after nicotine+SARS-CoV-2 treatment, cells released high levels of TNFα, IL6, IL8, and IL10, similarly to what is observed in COVID-19 patients with high disease severity and mortality." (PMID 36012747, 2022). "Overproduction of inflammatory cytokines (so-called cytokine storm) is observed in the severe COVID-19 patients, as evidenced by elevated serum levels of proinflammatory cytokines (in particularly, interleukin-6 (IL6) and tumor necrosis factor alpha (TNF)), and C-reactive protein (CRP)." (PMID 36741372, 2022). "Several prior studies also presented that the TNF-α levels in severe COVID-19 patients were significantly higher than non-severe COVID-19 patients." (PMID 35215138, 2022). "SOTRs with COVID-19 have higher plasma levels of cytokines such as IFN-λ1, IFN-γ, IL-15, IL-18 IL-1RA, IL-6, MCP-2, and TNF-α as compared to healthy controls, and the levels of GM-CSF, IL-15, IL-6, IL-8, and IL-10 were associated with disease severity in SOTRs." (PMID 35075453, 2022). "Significant levels of the inflammatory cytokines IL-6, IL-8, IL-10, and TNF-α have been documented in severe COVID-19 compared with non-severe disease cases, reflecting this phenomenon." (PMID 36556051, 2022). "The cellular differences in response to IL-1 versus TNF demonstrate that a cytokine-centric approach is unlikely to be successful to treat a disease like COVID-19, where there is a large array of cytokines induced." (PMID 34723652, 2022). "In patients with COVID-19 requiring intensive care, low CD4+ and CD8+ cell counts are also detected, negatively correlated with a high expression of cytokines (IL-6, IL-10, and TNF-α)." (PMID 35741174, 2022). "Furthermore, COVID-19 leads to elevated inflammatory markers, such as C-reactive protein (CRP), interleukin-6, and tumor necrosis factor alpha (TNF-α)." (PMID 35588115, 2022). "As a result, we found that the use of anti-TNF did not increase the frequency and severity of COVID-19." (PMID 36161620, 2022). "Indeed, elevated levels of various interleukins such asIL-6, IL-1β, TNF-α, IL-10, and IL-8 and the chemokine MCP1 have been well documented in patients with severe COVID-19." (PMID 36016187, 2022). "According to KEGG pathway enrichment analysis and literature, the molecular mechanism of puerarin in the therapy of EHF/COVID-19 may be related to HIF-1, TNF, IL-17, and Toll-like receptor signaling pathway." (PMID 35663983, 2022). "Cytokine storm of interleukin (IL)-2, IL-4, tumor necrosis factor-alpha (TNF-α), interferon-gamma (IFN-γ), and C-reactive protein has not been directly associated with COVID-19, whereas IL-6 and IL-10 were found to be COVID-19 severity predictors." (PMID 35054524, 2022). "Advanced disease is characterized by a hyper-inflammatory state, with high levels of circulating pro-inflammatory cytokines, such as Interleukin-6 (IL-6), Tumor Necrosis Factor-alpha (TNF-α) and interferon-gamma (IFN-γ), which have been blamed for the extensive COVID-19-related tissue damage." (PMID 36680091, 2022). "Significantly higher levels of IL-6, IL-8, and TNF-α in COVID-19 without HIV vs. HIV/COVID-19 patients (p < 0.05) were observed." (PMID 35891555, 2022). "Among the COVID-19 patients, HLH has become an unrecognized complication of an innate immune response by uncontrollable cytokine storm and enhanced quantity of IL-2, IL-6, IL-7, and TNF-α." (PMID 35165505, 2022). "The effect of this vaccine on cytokine production by monocytes in previously infected individuals was different from that seen in individuals that had never been infected, as neither IFN-γ nor TNF were increased by vaccination in COVID-19-recovered subjects." (PMID 36072604, 2022).
COVID-19 (continued). "We then investigated CD4+, Treg and CD8+ T cells polyfunctionality by analyzing simultaneous production of TNF-α, CD107a, IFN-γ, IL-2, IL-17, granzyme-B and TGF-β by mild, moderate and severe COVID-19 convalescent patients at recovery time-point I and time-point II, as well as by healthy donors." (PMID 35757700, 2022). "Another mechanism that may also be involved in the development of AKI in COVID-19 is the storm of pro-inflammatory cytokines (IFN-γ, IL-6, IL-8 and TNF-α) induced by SARS-CoV-2, which activates nuclear factor kappa B (NF-kB)." (PMID 37675003, 2022). "Based on the Surveillance Epidemiology of Coronavirus Under Research Exclusion for Inflammatory Bowel Disease (SECURE-IBD) and J-COSMOS data, older age and the use of steroids contributed to the severity of COVID-19, while anti-TNFα agents did not." (PMID 36417106, 2022). "Therefore, we analyzed the viral loads and the differential gene expression profiles of eight cytokines (IL-1, IL-2, IL-4, IL-6, IL-10 IFN-γ, TNF-α, and TGF-β1) in a total of 118 qPCR confirmed COVID-19 cases." (PMID 36584119, 2022). "Overall, patients with COVID-19 using anti-TNF therapy do not fare worse than those treated with other drugs." (PMID 35223745, 2022). "Here, we present the result of a systematic review and, whenever possible, a meta-analysis of IFITM3, FURIN, ACE1, and TNF-α genetic association with susceptibility to SARS-CoV-2 infection and COVID-19 severity." (PMID 35432458, 2022). "Once recruited in the site of infection, neutrophils release different proinflammatory mediators, including cytokines (interferon-α, interferon-β, tumor necrosis factor, and interleukins 1β, 6, and 10) and chemokine (e.g., CXCL10) that participate in COVID-19 pathogenesis." (PMID 35336077, 2022). "Current clinical studies have shown that the expression levels of inflammatory factors (IL-2, IL-7, IFN-γ, and TNF-α) positively correlate with the severity of COVID-19, suggesting that PLA2G4A may be a key target in the development of COVID-19." (PMID 36210820, 2022). "A recently published study showed that nonsurvivor COVID-19 patients had increased levels of LPS, IL-6, and TNF-α, among others." (PMID 35563697, 2022). "However, galectin-9 plasma levels also correlated with pro-inflammatory mediator secretion (IL-6, TNFα, CXCL10) in dengue and COVID-19 infected patients." (PMID 36142892, 2022). "This decreased expression of certain cytokines (IL-2, IL-6, TNF-α, and IFN-γ) in the nasopharyngeal milieu may be considered early biomarkers for disease severity in COVID-19 patients." (PMID 36584119, 2022). "Interleukin (IL)-1, IL-6, IL-10, tumor necrosis factor-alpha (TNF-a), interferon-gamma (IFN-γ), chemokine (C-C motif) ligand 2 (CCL-2), CXCL-9, and IL-8 are some of the additional cytokines found to be important in the pathophysiology of COVID-19." (PMID 35632654, 2022). "In addition, tumor necrosis factor alpha (TNF-α), a proinflammatory cytokine, is upregulated in COVID-19 patients with severe symptoms." (PMID 36478862, 2022). "To sum up, FCGR3A, TNF, and CCL3 might be potential biomarkers for COVID-19-related CU, and the common pathways and related molecules we explored in this study might provide new ideas for further mechanistic research." (PMID 36531995, 2022). "Six patients using anti-TNF (2 adalimumab, 1 etanercept, 1 golimumab, infliximab) and 3 nonuser patients recovered from COVID-19 (p = 0.999)." (PMID 36161620, 2022). "Furthermore, TUG1 had a positive correlation with CCL2 and TNF-α, implying that TUG1 is involved in CCL2 and TNF-α production, which explains its role in COVID-19." (PMID 35982898, 2022). "Therefore, our primary aim was to investigate the association between found SNPs, IL-6 (rs1800796), IL-10 (rs1800896), TNF-α (rs1800629), and IFITM3 (rs12252) and the presence of post-COVID pain in individuals previously hospitalized by COVID-19." (PMID 36233516, 2022).